ITPR3 (inositol 1,4,5-trisphosphate receptor type 3)
Diseases named in the same sentence as ITPR3 in open-access papers (continued):
Sharing a sentence is not in itself a finding about the gene and the disease.
neuroblastoma (3 papers, 2017 to 2023). Neuroblastoma (NB) is the most common solid, extracranial childhood tumor. "Expression of ITPR1 and ITPR3 transcripts was as well deregulated in SH-SY5Y neuroblastoma cells upon treatment with CDDP or TOPO this effect was also observed for both treatments in IMR-32 cells and for CDDP treatment in NLF cells." (PMID 28206967, 2017).
pancreatic cancer (3 papers, 2021 to 2024). "Up-regulated ITPR2 and ITPR3 were associated with higher pathological stages of pancreatic cancer." (PMID 35580861, 2022). "We noticed that genes correlated to ITPR3 expression in pancreatic cancer are also correlated to MYOF expression (R = 0.82), while it was not the case in healthy pancreas (R=-0.097)." (PMID 38368370, 2024). "The electron microscope assay was employed to explore the role of ITPR3 in pancreatic cancer cell lines’ endoplasmic reticulum stress." (PMID 35580861, 2022). "In summary, our findings demonstrated that ITPR3 has the potential to be drug targets and biomarkers for human pancreatic cancer." (PMID 35580861, 2022). "Noteworthily, ITPR3 was significantly upregulated in pancreatic cancer patients in six datasets with low p-value much lower than 0.05, such as 1.83e-7, 6.03e-8." (PMID 35580861, 2022). "In summary, our study suggested that ITPR3 is a potential target and new biomarker for the prognosis of pancreatic cancer." (PMID 35580861, 2022). "As Kaplan-Meier Plotter analysis demonstrated, decreased expression of ITPR2 and ITPR3 indicated better overall survival for patients with pancreatic cancer." (PMID 35580861, 2022). "To evaluate the function of ITPRs on the cancer patient’s clinicopathological and survival, we investigated survival analysis of ITPR1, ITPR2, and ITPR3 for pancreatic cancer by using Kaplan-Meier Plotter and GEPIA databases." (PMID 35580861, 2022). "Then, we evaluated these findings in PAAD patients suggested that ITPR3 may be a robust factor in pancreatic cancer pathogenesis may sever as new drug targets and promising prognostic biomarkers for high pancreatic pathological cancer stage and poor disease outcome." (PMID 35580861, 2022). "Secondly, we used Kaplan-Meier Plotter and GEPIA databases to explore the prognostic value of ITPRs in pancreatic cancer: decreased ITPR2 and ITPR3 indicated better survival." (PMID 35580861, 2022). "In healthy condition, MYOF and ITPR3 expressions were not correlated (R = 0.058, p-value: 0.0017), while in pancreatic cancer their expression appeared strongly and significantly correlated (R = 0.612, p-value: 1.09e-5)." (PMID 38368370, 2024). "This study found that ITPR1 and ITPR3 were up-regulated in pancreatic cancer, while there was no significant change in ITPR2." (PMID 35580861, 2022). "The result showed that ITPR1 and ITPR3 were up-regulated in pancreatic cancer specimens than non-tumor samples, confirming the previous results." (PMID 35580861, 2022).
anhidrosis (2 papers, 2020 to 2024). Lack of sweating or the ability to sweat when provoked by the appropriate stimulus. "Mutations in ITPR2 and ITRP3, respectively, encoding IP3R types 2 and 3, are associated with anhidrosis in patients, and the same phenotype is also observed in Itpr2 and Itpr3 double knockout mice." (PMID 33250786, 2020).
bladder cancer (2 papers, 2021 to 2022). "In bladder cancer tissues and cancer cells, ITPR3 was also highly expressed, resulting from the demethylation of the ITPR3 promoter region." (PMID 35580861, 2022). "A Matrigel invasion assay was conducted to assess the distant metastatic capacity of bladder cancer cells, and ITPR3 inhibition also suppressed the invasion ability of BCa cells." (PMID 33573671, 2021). "Our study clarifies that ITPR3 serves as an oncogene in bladder cancer cells and represents a novel candidate for bladder cancer diagnosis and treatment." (PMID 33573671, 2021). "It is worth noting that we demonstrated for the first time that ITPR3 was overexpressed and served as an oncogene in bladder cancer." (PMID 33573671, 2021). "The expression of ITPR3 in bladder cancer was analyzed using public databases and bladder cancer tissue microarrays." (PMID 33573671, 2021). "Through UALCAN TOOL, we found ITPR3 was in high expression in bladder cancer while the methylation level of ITPR3 was in low level." (PMID 33573671, 2021). "Herein, we elucidated a novel role of ITPR3 in regulating the proliferation, metastasis, and stemness of bladder cancer cells." (PMID 33573671, 2021). "In this study, we demonstrated for the first time that ITPR3 is abnormally overexpressed in bladder cancer tissues compared with normal tissues." (PMID 33573671, 2021). "In conclusion, we demonstrated in this research that ITPR3, as an oncogenic gene, promoted the proliferation, metastasis and stemness of bladder cancer through the NF-κB/CD44 signaling pathway." (PMID 33573671, 2021). "The methylation level of ITPR3 in SVHUC-1 cells was much higher than that in bladder cancer cells 5637 and 253 J." (PMID 33573671, 2021). "The expression of ITPR3 was knocked down by shRNA in 5637 and 253 J cells with relatively high ITPR3 expression to investigate the function of ITPR3 in bladder cancer, and the inefficiency of knockdown was detected by a western blot assay." (PMID 33573671, 2021). "From our work in this research, we demonstrated the oncogenic role of ITPR3 in bladder cancer in contrast to the roles of ITPR1 and ITPR2, whose proapoptotic effect was already described." (PMID 33573671, 2021). "ITPR3 promoted the proliferation of bladder cancer by accelerating cell cycle transformation and promoted local invasion and distant metastasis by inducing epithelial-to-mesenchymal transition (EMT)." (PMID 33573671, 2021). "Higher ITPR3 expression was found in bladder cancer tissues and bladder cancer cells compared with the corresponding normal peritumor tissues and SV-HUC-1 cells, which was attributed to demethylation in the ITPR3 promoter region." (PMID 33573671, 2021). "Therefore, we can conclude that demethylation of the ITPR3 promoter is responsible for its high expression in bladder cancer." (PMID 33573671, 2021). "Furthermore, to investigate the potential role of ITPR3 in the migration and invasion capacity of bladder cancer cells, wound healing assays and transwell assays were conducted simultaneously after ITPR3 knockdown." (PMID 33573671, 2021). "The revelations of the molecular mechanism and function of ITPR3 will be helpful in understanding the malignant progression of bladder cancer, in which ITPR3 might be a novel target for the diagnosis and treatment of bladder cancer, especially metastatic bladder cancer, in the future." (PMID 33573671, 2021). "However, the potential roles and molecular mechanism of ITPR3 in bladder cancer are still unclear." (PMID 33573671, 2021). "All these data suggested that ITPR3 might act as an important factor in bladder cancer metastasis." (PMID 33573671, 2021). "In addition, we found that ITPR3 accelerated the malignant progression of bladder cancer by promoting proliferation, metastasis, and cancer stemness in vitro and in vivo, and in this process, the role of the NF-κB/CD44 signaling pathway could not be neglected." (PMID 33573671, 2021).
bladder cancer (continued). "We demonstrated that ITPR3 depletion suppressed cancer cell proliferation, migration, invasion and stemness by inhibiting the expression of CD44, which is the main cancer stem cell marker in bladder cancer." (PMID 33573671, 2021).
combined immunodeficiency (2 papers, 2023 to 2025). A broad classification of inherited disorders presenting at birth that affect both the cell-mediated and humoral aspects of the immune response. "Recently, both autosomal dominant and recessive ITPR3 mutations have been reported in association with combined immunodeficiency (CID), accompanied by multisystem manifestations including neurological involvement." (PMID 41019080, 2025).
depression (2 papers, 2021 to 2024). "Additional studies are needed to assess the interrelationship between ITPR3, vasopressin, inositol, calcium and depression." (PMID 33414381, 2021).
epilepsy (2 papers, 2020 to 2024). A brain disorder characterized by episodes of abnormally increased neuronal discharge resulting in transient episodes of sensory or motor neurological dysfunction, or psychic dysfunction. "More significantly, PIK3R1 and ITPR3 were also significantly differentially expressed in the hippocampus of epilepsy group, compared with HC group." (PMID 39911741, 2024). "In expression level validation and anti-epileptic drug responsiveness analysis, PIK3R1 and ITPR3 had significant differences in the hippocampus of patients with epilepsy." (PMID 39911741, 2024). "This study was the first to determine that ITPR3 showed differential expression in the peripheral blood and hippocampus of epilepsy patients, which might play a role in regulating the level of autophagy by modulating neuronal calcium homeostasis." (PMID 39911741, 2024). "Therefore, PIK3R1 and ITPR3 had significant differences in peripheral blood and brain tissue of patients with epilepsy, and had potential as biomarkers in epilepsy." (PMID 39911741, 2024).
head and neck squamous cell carcinoma (2 papers, 2020 to 2021). A squamous cell carcinoma that arises from any of the following anatomic sites: lip and oral cavity, nasal cavity, paranasal sinuses, pharynx, larynx, and salivary glands. "Other studies associated the expression level of ITPR3 with the aggressiveness of different types of tumors, including colorectal carcinoma, gastric cancers, and head and neck squamous cell carcinoma." (PMID 32290556, 2020).
Hypertension (2 papers, 2022 to 2025). The presence of chronic increased pressure in the systemic arterial system. "ITPR3, encoding inositol 1,4,5-trisphosphate receptor type 3, was previously associated with hypertension in rodent studies." (PMID 35213289, 2022). "Elevated serum levels of ETS1 and ITPR3 could be used in routine screening for high‐risk individuals, such as the elderly or those with hypertension, smoking or a family history of AAA." (PMID 39823264, 2025).
metabolic syndrome (2 papers, 2022 to 2025). A cluster of metabolic risk factors for CARDIOVASCULAR DISEASES and TYPE 2 DIABETES MELLITUS. "The BTBR mouse model, with its unique Itpr3 gene mutation, exhibits core autism-like behaviors and metabolic syndromes, providing valuable insights into ASD pathophysiology." (PMID 40869971, 2025).
neuropathy (2 papers, 2025). A disorder affecting the nervous system that manifests with pain, tingling, numbness, and/or muscle weakness. "Together, these data suggest a genotype-phenotype relationship for ITPR3 variants in dogs and humans, where the mildest dominantly inherited variants may lead to neuropathy while more severe variants produce multisystem involvement." (PMID 39804930, 2025). "Previously, a few other cases of neuropathy associated with ITPR3 variants of unknown significance had been reported." (PMID 39804930, 2025). "Interestingly, the heterozygous ITPR3-T1424M mutation in the ARM2 domain, associated with neuropathy, when stably expressed in HEK-3KO cells also exhibited spontaneous Ca2+ puffs." (PMID 39947469, 2025). "Analogously to the dogs described here, one individual in her 50s who carried the ITPR3 p.T1424M variant had no signs of neuropathy but widespread slowing of NCV, confirming the presence of subclinical neuropathy." (PMID 39804930, 2025).
Sepsis (2 papers, 2018 to 2021). Sepsis is defined as life-threatening organ dysfunction caused by a dysregulated host response to infection. "In the GSE54514 control and sepsis groups, CD3D and ITPR3 (inositol 1,4,5 trisphosphate receptor type 3) had degree 33 and 43, respectively." (PMID 33667236, 2021).
Sjögren’s syndrome (2 papers, 2014 to 2024). "Inflammatory cell infiltration into the lacrimal glands and elevation of serum autoantibodies, a representative marker for Sjögren’s syndrome (SS) in humans, were also detected in older Itpr2−/−;Itpr3−/− mice." (PMID 24901844, 2014). "In addition, we detected abnormalities in Itpr2−/−;Itpr3−/− lacrimal gland tissues, such as inflammation, infiltration, and elevated autoantibodies, and these abnormalities mimic human Sjögren’s syndrome (SS)." (PMID 24901844, 2014).
Autoimmunity (1 paper, 2025). The occurrence of an immune reaction against the organism's own cells or tissues. "Compared with subcluster 1 of plasma cells, subcluster 0 cells had higher levels of positive autoimmune antibodies and autoimmunity ability, with higher expression of ITPR3 and ADA." (PMID 40904455, 2025).
bipolar disorder (1 paper, 2022). A disorder of the brain that causes unusual shifts in mood, energy, activity levels and the ability to carry out day-to-day tasks. "Likewise, the profiles of genes in the inositol 1,4,5-trisphosphate receptor family, including ITPR1, ITPR2, and ITPR3, were impacted by MIA, and members of this family have been associated with neurological and motor function impairment and bipolar disorder." (PMID 36011282, 2022).
cervical cancer (1 paper, 2017). A primary or metastatic malignant neoplasm involving the cervix. "In this study, we investigated the association of ITPR3 rs3748079 A/G and rs2229634 C/T SNPs and their haplotypes with the cervical cancer risk in Taiwanese women." (PMID 28036301, 2017). "We aim to investigate if ITPR3 genetic polymorphisms are associated with the risk of cervical cancer in Taiwanese women." (PMID 28036301, 2017). "We therefore tested the hypothesis that specific ITPR3 SNPs are associated with cervical cancer risk with an association study of 462 cervical squamous cell carcinoma (CSCC) patients and 921 healthy controls." (PMID 28036301, 2017). "Because ITPR3 locates at about 500kb centrometric to the class II HLA genes DR and DQ, which are found to associate with cervical cancer, it is important to clarify whether association between ITPR3 AT haplotype and CSCC is dependent on LD with class II HLA genes." (PMID 28036301, 2017).
cervical squamous cell carcinoma (1 paper, 2017). A squamous cell carcinoma arising from the cervical epithelium. "ITPR3 rs3748079 A/G and rs2229634 C/T polymorphisms were genotyped in a hospital-based study of 462 women with cervical squamous cell carcinoma (CSCC) and 921 age-matched healthy control women." (PMID 28036301, 2017).
channelopathies (1 paper, 2025). "In-depth immunophenotyping and functional characterization, together with compelling clinical overlap with the non-immunological features seen in STIM1/ORAI1 channelopathies, such as ED and peripheral neuropathy, establish monoallelic missense variants in ITPR3 as a cause of syndromic CID." (PMID 39560673, 2025).
clear renal cell carcinoma (1 paper, 2020). "An increased expression of ITPR3 was detected in clear renal cell carcinoma compared to the unaffected part of the kidney; ITPR3 silencing affected tumor growth, in vitro as well as in vivo, providing a direct proof of the involvement of this receptor in the carcinogenesis." (PMID 32290556, 2020).
coronary artery disease (1 paper, 2020). "More in general, ITPR3-mediated pathways have been also linked to ischemic heart disease and coronary artery disease." (PMID 32290556, 2020).
Dystonia (1 paper, 2023). An abnormally increased muscular tone that causes fixed abnormal postures. "Both its mutation and the ANO3 mutation are associated with myoclonus‐dystonia.Although both ITPR3 and CACNA1B act on cytoplasmic calcium ion concentration, the specific effects of these mutations have not been confirmed in vivo, warranting further study." (PMID 37649308, 2023).
endometrial cancer (1 paper, 2022). Primary or metastatic malignant neoplasm involving the endometrium (mucous membrane that lines the endometrial cavity). "Further, we analyzed the enriched RNAs in apoptosis pathways, and the CPTAC database showed that their encoded proteins were upregulated in endometrial cancer tissues, including ITPR3, LMNB1, PARP1, PARP4, and TUBA1C." (PMID 36566215, 2022). "Then we analyzed the RNAs enriched in the apoptotic pathway through CPTAC database, and showed that the protein level of ITPR3, LMNB1, PARP1, PARP4, and TUBA1C were upregulated in endometrial cancer tissues." (PMID 36566215, 2022).
hemophagocytic lymphohistiocytosis (1 paper, 2025). "We describe two cases of heterozygous ITPR3 mutations associated with Epstein-Barr virus-induced hemophagocytic lymphohistiocytosis (EBV-HLH), including one fatal outcome." (PMID 41019080, 2025). "We retrospectively analyzed the clinical characteristics of two patients with ITPR3 deficiency accompanied by hemophagocytic lymphohistiocytosis (HLH) at our center." (PMID 41019080, 2025).
Kawasaki disease (1 paper, 2023). A rare inflammatory disease characterized by an acute febrile, systemic, self-limiting, medium-vessel vasculitis primarily affecting children. "Elevated ESR and CRP levels are an important marker for the acute stage of Kawasaki disease (KD), and a polymorphism in ITPR3, whose protein product mediates the release of intracellular calcium, was associated with increased serum CRP levels in KD patients." (PMID 37238156, 2023).
liver fibrosis (1 paper, 2022). "In addition, we found that other CHB-related loci, such as HSD17b8, ITPR3, NUP205, RING1, and SKIV2l, were upregulated or downregulated in different ways in the groups with different degrees of liver fibrosis." (PMID 36406135, 2022).
lung diseases (1 paper, 2025). "Similarly, ITPR3, a gene associated with calcium signaling, has shown relevance in COPD through its regulation of intracellular Ca2+ release, affecting processes such as cell apoptosis and chemoresistance in lung diseases." (PMID 40045538, 2025).
lymphopenia (1 paper, 2025). Reduction in the number of lymphocytes. "In contrast to the typically normal T cell counts in CRAC channelopathies, ITPR3 patients have peripheral T cell lymphopenia alongside markers of poor thymic output including negligible RTEs and TREC levels." (PMID 39560673, 2025). "Whereas our study further emphasizes that SOCE is critical for the development of unconventional T cell populations, including Treg, iNKT cells and γδ T cells, profound lymphopenia of conventional T cells is a hallmark feature in patients with ITPR3 variants, but not in CRAC channelopathies." (PMID 39560673, 2025). "Due to profound lymphopenia, it was not possible to assess ITPR3 protein expression in primary lymphocytes." (PMID 39560673, 2025).
metastatic tumors (1 paper, 2022).
Obesity (1 paper, 2020). Accumulation of substantial excess body fat. "Finally, in the Hispanic population, ITPR1 was associated to the pathophysiology of childhood obesity, while ITPR3 was linked to body mass index variants conferring a high risk of extreme obesity." (PMID 32290556, 2020).
parasitic infection (1 paper, 2022). "Jaw1 and ITPR2 are expressed in small intestinal tuft cells, chemosensory cells that detect parasitic infection, Jaw1 and ITPR3 in tongue epithelial taste cells that perceive taste, and Jaw1 and ITPR2/3 in pancreatic acinar cells that secrete digestive enzymes." (PMID 35676525, 2022).
primary biliary cholangitis (1 paper, 2018). Primary biliary cholangitis (PBC) is a chronic and slowly progressive cholestatic liver disease of autoimmune etiology characterized by injury of the intrahepatic bile ducts that may eventually lead to liver failure. "Finally, miR-506 also inhibits ITPR3 expression in cholangiocytes, and this contributes to their loss in patients with primary biliary cholangitis." (PMID 30563259, 2018).
Sensorimotor neuropathy (1 paper, 2025). "The human disease CMT1J, caused by pathogenic variants in ITPR3, is typically a slowly progressive sensorimotor neuropathy." (PMID 39804930, 2025).